OAS3 (2'-5'-oligoadenylate synthetase 3)
Diseases named in the same sentence as OAS3 in open-access papers (continued):
Sharing a sentence is not in itself a finding about the gene and the disease.
neuroblastoma (1 paper, 2023). Neuroblastoma (NB) is the most common solid, extracranial childhood tumor. "Here, we describe the protein expression levels of OAS1, OAS2, OAS3, and OASL in cells forming the NVU, such as primary human brain pericytes, astrocytes, EC, immortalized human microglial cells, and SH-SY5Y neuroblastoma cell line." (PMID 37209263, 2023). "Our studies also revealed a prominent expression of OAS2, OAS3, and OASL in SH-SY5Y cells; however, this is an immortalized neuroblastoma cell line, which does not fully represent mature neurons." (PMID 37209263, 2023).
osteosarcoma (1 paper, 2022). A usually aggressive malignant bone-forming mesenchymal neoplasm, predominantly affecting adolescents and young adults. "To investigate the intracellular localisation of OAS3, we assessed the distribution of OAS3 in the endoplasmic reticulum (ER) and microtubules of A431, A549, and U-2 osteosarcoma (OS) cells using an indirect immunofluorescence assay." (PMID 35592250, 2022).
pancreatic ductal adenocarcinoma (1 paper, 2022). An infiltrating adenocarcinoma that arises from the epithelial cells of the pancreas. "In Badea Pancreas dataset, OAS3 was upregulated with a fold change of 2.540 in pancreatic ductal adenocarcinoma." (PMID 35719943, 2022).
renal carcinoma (1 paper, 2018). A carcinoma arising from the epithelium of the renal parenchyma or the renal pelvis. "Small RNA-induced knockdown of GAPDH in renal carcinoma cells was accompanied by increased expression of IFI6, OAS3, and UBE2L6." (PMID 30253781, 2018).
reovirus infection (1 paper, 2017). "Not surprisingly, reovirus infection stimulated a strong increase in genes associated with an anti-viral response in both cell lines, including OAS1, OAS2, and OAS3." (PMID 29156834, 2017).
Salmonella Infections (1 paper, 2016). Infections with bacteria of the genus SALMONELLA. "Interestingly, these cis eQTL showed a much stronger effect in infected macrophages (best Psalmonella = 3.5 × 10−3 versus best Pnon-infected = 0.027), supporting an interaction between the Neandertal haplotype and the OAS3 response to Salmonella infection." (PMID 27899133, 2016).
infection (42 papers, 2012 to 2026). The state of being infected such as from the introduction of a foreign agent such as serum, vaccine, antigenic substance or organism. "As key ISGs, OAS1, OAS2, and OAS3 are evolutionarily conserved and are associated with the early inflammatory response during infection." (PMID 34490145, 2021). "Specifically, upon infection with West Nile, Sindbis, Influenza, or Vaccinia viruses, OAS3 plays the dominant role in RNase L activation, while OAS2 fulfills that role in the context of Zika virus infection." (PMID 40312500, 2025). "OAS2 and OAS3 recognize dsRNA in different ways, which provides an additional means of activating RNase L, potentially reducing OAS1 activity loss during infection." (PMID 36670749, 2023). "The activation of RNase L is dependent on OAS3 expression during infection with diverse human viruses, and it can be induced by smaller amounts of double-stranded RNA (dsRNA)." (PMID 36670749, 2023). "It has been reported that upon viral or bacterial infection, the IFN signaling activation induces the production of the 2′-5′-oligoadenylate synthetase (OAS) family, which includes the OAS3 gene, that was upregulated by infection with rBCG-LTAK63." (PMID 35746439, 2022). "The ratio of OAS3/Tubulin gradually decreased from 48 to 72 ​h post-infection (h.p.i) in EV71 infected pLKO.1 ​cells." (PMID 35504537, 2022). "OAS1, OAS2, OAS3, and OASL expression levels are also directly linked to mycobacterial pathogenicity during the early post-infection period, as they can restrict MTB intracellular replication in macrophages by regulating cytokine secretion." (PMID 34490145, 2021). "Genes encoding interferons (Ifnb, Ifnl2 and Ifnl3), chemokines (Ccl7, Ccl5, and Cxcl10), and ISGs (Ifit1, Ifit2, Ifit3b, Oas3, Ifi44, Rsad2, and Isg15, among others) were prominently represented among those induced by infection in Ifnar1-/- mice." (PMID 34591933, 2021). "Previous studies showed significant association between OAS2, OAS3, and OASL expression and IFNα level during infection of virus or bacteria." (PMID 32321151, 2020). "We found that cells from people with the Neandertal-like haplotype express lower levels of OAS3 upon infection, as well as distinct isoforms of OAS1 and OAS2." (PMID 27899133, 2016). "Within metabolic inflammation, convergent evidence also implicates the IFN-OAS axis in T2DM: in human skin and skeletal muscle transcriptomes, OAS1/OAS2/OAS3 are significantly upregulated and enriched for infection-related pathways, indicating tissue-level activation of interferon responses in T2DM." (PMID 41569989, 2026). "Interestingly, this increase was gradually reduced over time, and only OAS2 and OAS3 showed a slight increase in mRNA expression after 72 h of infection as compared to mock infection." (PMID 37209263, 2023). "Finally, we demonstrated that infection induces transcription of cytosolic innate immune sensors Mx1, Oas1, and Oas3 in vivo and in vitro." (PMID 36678402, 2022). "Infection with splicing-defective ΔE4 mutant leads to dsRNA accumulation and activation of both PKR and OAS3/RNase L, promoting formation of RLB-like granules." (PMID 41756847, 2026). "Infection with 60 ng/ml of HIV-1 for 24 or 48 h resulted in a significant increase in the expression of OAS1, OAS2, OAS3, and OASL at the mRNA level." (PMID 37209263, 2023). "To evaluate type I interferon responses earlier in infection, we examined the abundance of interferon-induced protein 44 (IFI44) and OAS-3 at 6 and 9 dpi by qPCR." (PMID 34928716, 2022). "Some interferon stimulated genes such as OAS1, OAS3, MX1, and RSAD2 that were strongly induced by rDEN2Δ30 infection are also known to be regulated in natural infection." (PMID 34031380, 2021). "By 72 h post-infection, although only five common genes (IFI44, OASL, OAS3, IRF9, IRF7) are identified, these genes contribute significantly to a range of crucial GO processes, emphasizing the depth of the immune response despite the limited number of genes involved." (PMID 38957806, 2024).
infection (continued). "In contrast to changes in mRNA levels, protein levels of OAS2 and OAS3 remained elevated in infected pericytes even after 48 and 72 h post infection, and OASL protein expression did not change as the result of infection." (PMID 37209263, 2023). "Upon infection, this cluster enriched a strong interferon-stimulated gene (ISG) signature, including master antiviral regulators Irf7, Oas3, and Isg15, suggesting induction of the ISG program could occur in neutrophils under severe conditions." (PMID 35420442, 2022). "For example, heat-iMVA infection triggered higher levels of IFN-inducible genes than MVA, including Ifih1 (MDA5), Ddx58 (RIG-1), Oasl2, Oas3, TLR3, Nod1, Ifna4, Ifnb1, Ccl5, Cxcl9, Cxcl10, and members of the guanylate binding protein (Gbp) family, as largely dependent on STING (marked as b)." (PMID 36261460, 2022). "Infections in the RNAseL k/o cells were again largely confined to perinuclear regions of the cytoplasm, while E7 RNA FISH signals developed throughout the cytoplasm between the 2 and 6 h time points in the ZAP and OAS3 k/o cells." (PMID 31276592, 2019). "We show that the expression of the interferon-stimulated proteins MX1, IFIT1, IFIT3 and ISG15, as well as expression of defense response proteins DDX58, STAT1, OAS3, EIF2AK2 and SAMHD1 was significantly up-regulated in these cells upon infection with either virus." (PMID 30959732, 2019). "We found that, in addition to a broad induction of ISGs (for example, DTX3L, OAS3, RTP4, IRF7, MX2, IFIT3, IFIH1), only IFNB1 and, more robustly, IFNL1-like and IFNL3-like were induced in virus-infected organoids at 1 and 3 days after infection compared to the uninfected controls." (PMID 40399606, 2025). "In the present study, we observed that several ISGs with known or proposed anti-CCHFV activity, i.e., Mx1, ISG15 and ISG20 or not defined for CCHFV like IFIT1, IFIT3, IFITM3, IFI16, and OAS3 were upregulated in the acute phase CCHFV patient samples as well as in the cell-infection model." (PMID 35437144, 2022). "Thus, in RoNi/7 bat cells, as in human cells, activation of RNase L during infection and its antiviral activity are dependent primarily on OAS3 while MAVS signaling is not required for the activation of RNase L and restriction of infection." (PMID 31719180, 2019). "Thus, activation of RNase L during VACVΔE3L infection of bat RoNi/7 cells was dependent on RNase L and OAS3 but not OAS1, OAS2, or MAVS, similar to our findings with SINV." (PMID 31719180, 2019). "Similar to the lab-adapted strains, we observed six ISG-related DAPs (IFIT1, IFIT2, IFIT3, OAS3, ISG15, and MX1) significantly upregulated compared to MOCK infected UNOs, upon infection with clinical isolates of PeV-A3, but not PeV-A1." (PMID 38514653, 2024). "Although OAS3 has been observed to inhibit the replication of many EVs, CA16 infection does not seem to downregulate the protein level of OAS3 in pLKO.1 ​cells." (PMID 35504537, 2022). "Sindbis virus (SINV) or vaccinia virus (VACVΔE3L) infection of wild-type (WT) or OAS1-KO (knockout), OAS2-KO, or MAVS-KO RoNi/7 cells, but not RNase L-KO or OAS3-KO cells, induces robust RNase L activation." (PMID 31719180, 2019). "Regardless of dexamethasone treatment or time post-infection, expression of ISGs of the OAS family, specifically OAS2, OAS3 and OASL, and its downstream RNaseL, were highly upregulated." (PMID 31635289, 2019). "The absence of MAVS and OAS3 in the HEK293 overexpression pulldown likely reflects limitations of this system, as certain interactions may only occur under infection conditions or in a cell type dependent manner." (PMID 40883306, 2025).
tumor (20 papers, 2009 to 2026). "Comprehensive molecular profiling further identified significant associations between OAS3 expression levels and key genomic features (tumor mutation burden, homologous recombination deficiency and RNA modification-related proteins)." (PMID 41700140, 2026). "In this study, we performed a pan-cancer analysis to examine the expression profiles of OAS3 in different cancer tissues and identify its underlying molecular mechanisms in the clinical prognosis of tumours." (PMID 35592250, 2022). "This study showed that OAS3 is highly expressed in various tumours, and high OAS3 expression is associated with poor survival outcomes." (PMID 35592250, 2022). "A close association was observed between OAS3 and pathways including tumour inflammation signature, cellular response to hypoxia, tumour proliferation signature, angiogenesis, and apoptosis." (PMID 35592250, 2022). "OAS3 mRNA was found to be significantly mutated in TGCT, ACC, COAD, and other tumours, suggesting that mutated OAS3 plays a key role in promoting the development of these tumours." (PMID 35592250, 2022). "We obtained OAS3 mutation data of various tumours from the UCSC Xena database." (PMID 35592250, 2022). "The molecular mechanisms underlying the role of OAS3 in the immune microenvironment and pathogenesis of different tumours remain unknown." (PMID 35592250, 2022). "The findings suggest that OAS3 is aberrantly expressed in almost all TCGA cancer types and subtypes and is associated with tumour staging, metastasis, and prognostic deterioration in different tumours." (PMID 35592250, 2022). "In addition, the innate immune response‐associated genes, including Oas1a, Oas2, Oas3, Ifi202b, Irf7, and Tlr9, were all down‐regulated, indicating a deficiency in anti‐tumor immune response." (PMID 31602788, 2019). "Further analyses demonstrated that OAS3 expression was correlated with immune-related genes, immune checkpoints, tumor stemness, and immune cell infiltration across multiple tumor types." (PMID 41700140, 2026). "The expression patterns of OAS3 were found to be stage-specific and cancer-specific across multiple tumor types." (PMID 41700140, 2026). "For instance, the male-amplifier cg12560128 was negatively correlated with OAS2 and OAS3 in COAD, both known immune biomarkers linked to the tumor microenvironment." (PMID 39716176, 2024). "High OAS3 expression was correlated with worse DFS in four types of tumours, including KIRP and PAAD." (PMID 35592250, 2022). "The expression of OAS3 was positively correlated with that of immune checkpoint-related genes in most tumours, suggesting that OAS3 is involved in the regulation of tumour immune response through the regulation of immune checkpoint activity." (PMID 35592250, 2022). "In TCGA data, differences in OAS3 expression were significant among 17 of the 33 cancer types analysed (except for KICH, in which OAS3 expression was lower than that in most tumour tissues)." (PMID 35592250, 2022). "The results of western blotting was consistent with those of qRT-PCR: OAS3 was highly expressed in tumor tissues in LIHC, LUAD, KIRP, and low in normal tissues." (PMID 35592250, 2022). "In the present study, we have systematically investigated and confirmed the role of OAS3 in tumour immune infiltration, immune escape, tumour progression, response to treatment, and prognosis of different cancer types using various bioinformatics methods." (PMID 35592250, 2022). "We found that OAS3 had a significant positive correlation with RNA methylation-related genes (m1A, m5C, and m6A) in most tumours." (PMID 35592250, 2022). "The OAS3 has also been reported to play a role in inhibiting tumour development by inducing apoptosis and anti-proliferative responses." (PMID 28344639, 2017). "In addition, the PML‐NB‐associated proteins, ISG20, OAS3, OAS1, and OASL were found to be upregulated and are considered to be tumour suppressors involved in promoting DNA cleavage, nuclear condensation, and apoptosis." (PMID 36579897, 2023).
tumor (continued). "OAS3 may influence tumour progression through immunosuppression." (PMID 35592250, 2022). "However, the expression and prognosis of OAS3 and tumour-infiltrating lymphocytes in pan-cancer remain unknown." (PMID 35592250, 2022). "Therefore, OAS3 may provide some help for tumour immunotherapy, thus facilitating the spread of tumours." (PMID 35592250, 2022). "Interestingly, neutrophils exhibited the highest correlation with OAS members (cor = 0.268 in OAS1; cor = 0.42 in OAS2; cor = 0.371 in OAS3; cor = 0.332 in OASL), highlighting the key role of OAS members associated with neutrophils in tumor immune infiltrating cells." (PMID 32560641, 2020). "IFI6, IFI27, OAS1, and OAS3 are part of the interferon-alpha response (IFN-α) pathway, known for its anti-tumor and anti-viral immune responses." (PMID 39809731, 2025). "The upregulation of OAS1, OAS3, and IFITM1 expression in various tumor cell lines is observed following multi-fraction irradiation." (PMID 38473966, 2024). "In seven types of tumours, including ACC and DLBC, patients with high OAS3 expression had worse DSS." (PMID 35592250, 2022). "The expression of representative ISGs including MX1, OAS3, and IFIT1 was found to be significantly higher in tumor cells compared to stroma cells." (PMID 34400640, 2021). "Consistently, CD44, OAS3, ISG15, STAT1, and WNT5A were significantly upregulated whereas KIT was significantly downregulated in tumor compared to normal in GSE13861." (PMID 30134903, 2018). "An interferon gene signature was also present in the profiles derived from the tumor epithelium of the ER-positive tumors (e.g., STAT1, IFIT1, IFIH1, IFI27, ISG15, OAS1, OAS3, OASL) and ER-negative tumors (e.g., HLA-DQA1 and HLA-DQB1)." (PMID 19225562, 2009). "In addition, a positive correlation was found between OAS3 and four immune pathway-related genes [receptor, MHC, immunoinhibitors and immunostimulators] in many tumour types." (PMID 35592250, 2022). "Results showed that the expressions of OAS2, OAS3, and OASL had significant negative correlations with tumor purity in BLCA." (PMID 36162993, 2022).